MPC2 (mitochondrial pyruvate carrier 2)
Diseases named in the same sentence as MPC2 in open-access papers (continued):
Sharing a sentence is not in itself a finding about the gene and the disease.
renal cell carcinoma (1 paper, 2020). "In kidney cancer, protein and mRNA levels for MPC1 and MPC2 are lower in advanced renal cell carcinoma (RCC) tumors compared to normal adjacent tissue, and decreased MPC1 expression in RCC correlates with worse survival outcomes." (PMID 32784379, 2020).
Renal cyst (1 paper, 2024). A fluid filled sac in the kidney. "On the other hand, the MPC1 (−1.5×)/MPC2 (−2.1×) heterodimer responsible for transporting pyruvate into the mitochondria for ATP production was downregulated in renal cysts." (PMID 39000280, 2024).
Sepsis (1 paper, 2025). Sepsis is defined as life-threatening organ dysfunction caused by a dysregulated host response to infection. "Gene expression of lactate dehydrogenase (Ldhb) and of the mitochondrial pyruvate carriers (Mpc1 and Mpc2) was also not affected by sepsis." (PMID 39821755, 2025).
tumor (20 papers, 2016 to 2025). "Using patient tumor microarray data (GSE10846), we found that the mRNA levels of MPC1 and MPC2, the genes that encode the MPC1 and MPC2 subunits of the MPC, were higher in OxPhos-DLBCLs." (PMID 36179030, 2022). "MPC complex regulated mitochondrial pyruvate flow inhibited the MPC1 and MPC2 expression in cancer cells and promoted glycolysis and lactate synthesis in tumor samples." (PMID 36213830, 2022). "According to the analysis on our TMA data, lower expression of MPC2 is correlated with a higher incidence of distant metastasis and lymph node invasion, bigger tumor size, low survival rate of patients, and advanced T stages." (PMID 33791391, 2021). "The sh-MPC2 (using shRNA#2) group displayed distinctly higher tumor weight than the control group, while that of the MPC2-OE group was lower compared to the vector group." (PMID 33791391, 2021). "Further, IHC assays of Ki67 in an orthotopic tumor revealed that knockdown of MPC2 promoted Ki67 expression while overexpression of MPC2 inhibited the expression." (PMID 33791391, 2021). "Cytoplasmic MPC1 and MPC2 proteins were highly expressed in 10 normal esophageal epithelia adjacent to tumor." (PMID 27911865, 2017). "Linear regression analysis further revealed that the MPC1 expression was positively correlated with the MPC2 expression in the PCA tumor tissues (r = 0.348, P =0.017)." (PMID 27852261, 2016). "In vivo, MPC2 silencing significantly reduced tumor growth in a xenograft mouse model." (PMID 40287899, 2025). "Mitochondrial pyruvate complex (MPC) comprised of pyruvate carriers 1 and 2 (MPC1/MPC2) is the entry point for pyruvate to the mitochondrial matrix for oxidative metabolism, and MPC deficiency contributes to tumor initiation and progression by enhancing glycolysis." (PMID 34980012, 2022). "The role of MPC2 in CRC growth was further assessed by an orthotopic tumor model." (PMID 33791391, 2021). "It has been reported that the effects of glycolysis on tumor progression can be diminished by diverting the metabolite pyruvate from conversion to lactate in part through transport into the mitochondria via the activity of the MPC1/MPC2 heterodimer." (PMID 34030708, 2021). "Our findings reveal MPC2 as a key regulator of mitochondrial function in DLBCL, promoting tumor progression through enhanced OXPHOS." (PMID 40287899, 2025). "MS-based proteomic profiling of tumor tissue samples (n = 45) demonstrated lower levels of both MPC subunits MPC1 (p = 0.024) and MPC2 (p = 0.018) in basal-like tumors." (PMID 39363341, 2024). "In contrast, six genes known to inhibit cell proliferation and tumor growth were overexpressed in d-HGP: SIRT6, MPC2, MIR4458HG, ST20-AS1, SREBF2, MRPL40." (PMID 38548918, 2024). "The mitochondrial pyruvate carrier (MPC) complex, which consists of MPC1 and MPC2, is required for efficient glucose production, and decreased MPC activity in tumors enhances glycolytic activity, resulting in tumor progression." (PMID 34980012, 2022). "Perhaps, it would be more appropriate to target tumor-specific or selective OXPHOS regulators, such as overexpressed PDKs, MPC2, or TEAD4." (PMID 34948229, 2021). "The expressions of MPC1 and MPC2 were then determined in 30 paired tumor and adjacent non-tumor tissues of OC using qRT-PCR analysis, as well as in another 205 paired tumor and adjacent non-tumor tissues of OC using IHC analysis." (PMID 38615083, 2024). "Low or absent MPC1 and MPC2 levels lead to metabolic disorders and alterations in tumor metabolism, and their restored expression inhibits tumor growth, invasiveness, metastasis, and stemness." (PMID 38926418, 2024). "Using a single-cell tumor-infiltrating lymphocyte (TIL) reference atlas, we observed that Mpc1 was significantly more expressed in progenitor exhausted (Tpex) than in terminally exhausted (Tex) TILs, whereas Mpc2 levels remained unaltered." (PMID 35452600, 2022).
tumor (continued). "The role of glycolytic pathways in tumor progression can be weakened by inhibiting the pyruvate to lactic acid conversion but transferring this metabolite to mitochondria through mitochondrial pyruvate complex (MPC) composed of two complexes: MPC1 and MPC2." (PMID 36213830, 2022). "In conclusion, we found downregulated MPC2 expression in CRC tissues, as well as a negative association of the expression with distant metastasis, patients' survival, lymph node invasion, T stage, and tumor size." (PMID 33791391, 2021). "Similarly, patients with positive expression of MPC2 in the tumor had significantly better OS than did patients with negative MPC2 expression in the tumor (P =0.02) according to Kaplan-Meier survival curves and the log-rank test." (PMID 27852261, 2016). "Moreover, it has shown in some studies that the expression levels of MPC1 and MPC2 in cancers are decreased, and low expression is correlated with poor survival in multiple cancers, including colon, kidney and lung, illustrating the regulation of MPC complex is pivotal for tumor cell growth." (PMID 27852261, 2016).
cancer (12 papers, 2016 to 2024). A tumor composed of atypical neoplastic, often pleomorphic cells that invade other tissues. "The downregulation of MPC1 and MPC2 has been associated with a pro-tumorigenic phenotype and in many cancers a poor clinical outcome." (PMID 33804985, 2021). "Positive MPC1 or MPC2 expression in cancer tissues was significantly associated with higher OS (P < 0.05)." (PMID 27852261, 2016). "It has been reported that the expression of MPC1 and MPC2 is frequently decreased in several types of cancer." (PMID 38615083, 2024). "For MPC1, the middle section was the predominant location for cancer cells, whereas the upper part also contributed significantly to MPC2 and MPC3 expression." (PMID 38486026, 2024). "An increasing number of studies have elucidated the potential role played by MPC2 in cancer cell proliferation and migration." (PMID 37580825, 2023). "According to the dataset from TCGA and the GEO, compared with paired tissue adjacent to cancer, the mRNA expression of MPC2 decreased in CRC tissues." (PMID 33791391, 2021). "IHC staining in a TMA containing 392 CRC specimens and paired corresponding tissue adjacent to cancer was performed to validate the protein level of MPC2." (PMID 33791391, 2021). "For example, the acetylation of lysine residues 45 and 46 in MPC1, or of lysines 19 and 26 in MPC2, was associated with reduced MPC activity in cancer and in the diabetic heart, respectively." (PMID 33804985, 2021). "The result of TMA analysis also showed substantially lower MPC2's protein expression in CRC tissues than those in tissues adjacent to cancer, and CRC tissues manifested a lower staining score." (PMID 33791391, 2021). "To understand the potential importance of MPC function in human HCC, we analyzed MPC1 and MPC2 expression in The Cancer Genome Database (TCGA), a comprehensive multidimensional map of key genomic changes in 33 types of cancer." (PMID 31484072, 2019). "Our work also has immediate implications for the development of small-molecule-oriented therapeutics that specifically target MPC2 in pyruvate-related diseases such as cancer, Alzheimer’s disease, and diabetes." (PMID 29472561, 2018). "MPC2 expression is inconsistently altered in cancer and variably correlated with survival." (PMID 28397687, 2017). "Recent identification of MPC1 and MPC2, genes responsible for pyruvate uptake into the mitochondrial matrix, has added a new complexity to targeting pyruvate metabolism in human disorders, including cancer." (PMID 28397687, 2017). "In line with previous reports on other cancer types, this study revealed that in BCa, MPC1 was frequently deleted, while MPC2 was mostly amplified." (PMID 34980012, 2022). "Different authors now indicate that the repression or deletion of Mpc1 and Mpc2 is common in cancer, explaining the correlation between low MPC expression and poor survival seen in some cancers." (PMID 33804985, 2021).
kidney disease (1 paper, 2020). "Moreover, both MPC1 and MPC2 levels were significantly correlated with serum creatinine, BUN and eGFR in patients with DN, whereas no analogous trend was observed in nondiabetic kidney disease." (PMID 32664896, 2020). "Moreover, both MPC1 and MPC2 levels were significantly correlated with serum creatinine, BUN and eGFR in patients with DN, whereas no analogous trend was observed in the non-diabetic kidney disease group." (PMID 32664896, 2020).
MPC2 also shares sentences with these, for which no sentence is quoted: melanoma (2 papers); metabolic disorders (2); adenocarcinoma (1); Azoospermia (1); cholangiocarcinoma (1); chronic kidney disease (1); colon (1); colorectal tumor (1); diffuse large B-cell lymphoma (1); Hypertension (1); infection (1); ischemia (1); liver cancer (1); mucinous adenocarcinoma (1); ovarian tumor (1); sarcoma (1); type 2 diabetes (1).